COL6A3 (collagen type VI alpha 3 chain)
Diseases named in the same sentence as COL6A3 in open-access papers (continued):
Sharing a sentence is not in itself a finding about the gene and the disease.
tumor (95 papers, 2006 to 2026). "In gain- and loss-of-function studies, high Col6a3 levels increased tumor growth and metastatic activity and enhanced the proliferative, migratory, and invasive activities of LUAD cells." (PMID 40166934, 2025). "We applied 101 machine learning algorithms to evaluate the prognostic and immunological value of COL6A3+ tumor-associated fibroblasts (TAFs) and GPNMB+ monocyte-derived macrophages (MDMs) in multiple GBM cohorts and immunotherapy cohorts." (PMID 41174767, 2025). "For example, collagens, such as COL1A1, COL1A2, COL3A1, COL5A2, COL6A1, COL6A2, and COL6A3 are thought to mediate tumor progression and are associated with a poor prognosis in BCa." (PMID 37277784, 2023). "In additions, clusters 4, 7 and 10 expressed a variety of collagen proteins including COL1A1, COL1A2, COL3A1, COL6A1 and COL6A3, which have been previously linked to abilities of proliferation, invasion, metastasis and drug resistance of tumor cells." (PMID 37644609, 2023). "cDNA microarray analysis of a series of paired melanoma tumor and tumor-derived cell line samples revealed that a set of stromal genes, including the gene encoding the α3 chain of collagen VI, COL6A3, were systematically and significantly down-regulated in all cell lines (data not shown)." (PMID 18086302, 2007). "Functionally, SULT1E1+ subclones and COL6A3-mediated macrophage-tumor interactions emerged as potential key drivers of malignancy, recurrence, and radioresistance." (PMID 42073533, 2026). "A unique cluster of tumor cells in D‐TGCT is identified that regulated differentiation of CD34+ fibroblasts into MMP3+ fibroblasts or APOE+ fibroblasts via COL6A3 − (ITGAV + ITGB8) interaction." (PMID 40126353, 2025). "Mass spectrometric analysis of total and glycosylated peptides in parental and GGT-inactive tumor samples identified Col6 chain α3 (Col6a3), a component of the Col6 heterotrimeric molecule, as a candidate LH2 substrate." (PMID 40166934, 2025). "The results showed that the dense COL6A3 collagen around blood vessels tightly encircles T cells, forming a physical barrier that prevents T cells from penetrating the tumor core." (PMID 41174767, 2025). "Three type VI COLs (encoded by COL6A1, COL6A2, and COL6A3) and two type I COLs (encoded by COL1A1 and COL1A2) constituted a significant proportion of the human colon ECM in NAT (55.6%) and tumor (31.8%) tissues." (PMID 40032993, 2025). "Ectopic LH2 expression accelerated cell migration and tumor progression to a greater extent in parental than Col6a3 K2049R cells, indicating that Col6 K2049 is a critical effector of LH2." (PMID 40166934, 2025). "In this review, we focus on the role of type VI collagens, specifically COL6A3, in tumor development, progression, and metastasis." (PMID 41228242, 2025). "In The Cancer Genome Atlas (TCGA) pancancer database, LUAD is one of multiple tumor types in which Col6a3 mRNA levels are higher in malignant than normal tissues, whereas Col6a1 and Col6a2 are not differentially expressed." (PMID 40166934, 2025). "In summary, COL6A3 and ETP are powerful drivers of tumor growth that have potential as noninvasive diagnostic and prognostic tools for the clinical management of cancer." (PMID 41228242, 2025). "Col6a3 K2049 was deglucosylated in GGT-inactive tumor samples, and mutagenesis of Col6a3 K2049 phenocopied Col6a3 deficiency or LH2 GGT domain inactivation in LUAD cells." (PMID 40166934, 2025). "For example, as a tumor promoter, COL6A3, which is produced by the host gene COL6A3, plays a crucial role in the extracellular matrix and promotes tumor growth in CRC." (PMID 39452835, 2024). "As the role of COL6A3 is complex and can vary between cancer types and across tumor staging, the increase in expression of Col6a3 mRNA and protein in tumors treated with MSU-42011 and resultant effect on invasion and immunity merits further investigation." (PMID 36901727, 2023).
tumor (continued). "Endotrophin (ETP), a cleavage product of the COL6A3 chain, increases tumor stem cell-like cells though activating the anthrax toxin receptor 1 (ANTXR1)." (PMID 36167487, 2022). "From the TIMER web resource, the association between CDH11, COL6A3, EDNRA, and SERPINF1 immune signatures and tumor purity or numerous vital immune cells was revealed." (PMID 36595851, 2022). "It was noted that the expression of CDH11, COL6A3, EDNRA, and SERPINF1 were negatively associated with tumor purity." (PMID 36595851, 2022). "Mutations in other collagens, such as COL6A6, COL22A1, COL6A3, COL12A1, and COL14A1, were also noted in a variety of tumor types." (PMID 34584216, 2021). "In ERα+ BCs, compared to normal samples, the sixth exon of the collagen type VI alpha 3 chain coding gene (COL6A3) involved in an ES event (COL6A3_5_6_7_ES) exhibited a significantly higher inclusion level in tumor samples (dPSI = 0.49; p < 0.0001)." (PMID 34944881, 2021). "COL1 is found extensively in tumor stroma, and when combined with certain other common tumor microenvironment proteins (i.e., COL6A3, OPN, and IL-8) the frequency of AXL-expressing cells significantly increased." (PMID 29719832, 2018). "Overexpression of COL6A3 alternative transcript in all examined tumor types indicates its significant contribution to disease development and pathogenesis." (PMID 28105922, 2016). "Components of the basement membranes were found to be expressed by the tumor cells only (laminin chains α3, β3, γ2), by both compartments (laminin chains α5, γ1, COL6A3, HSPG2) or by the stroma (Nidogens 1 and 2)." (PMID 24618895, 2014). "Collagen 6A3 (Col6a3), a component of extracellular matrix, is often up-regulated in tumours and is believed to play a pro-oncogenic role." (PMID 24498316, 2014). "Our results are consistent with clinical studies showing that cancer cells with high levels of COL6A3 show a reduced response to platinum-based chemotherapy than tumours with low levels of COL6A3." (PMID 23629957, 2013). "The mRNA levels of COL6A3 in tumour tissues of PyMT mice were significantly increased in response to cisplatin treatment; this increase was dramatically suppressed by combination with TZDs." (PMID 23629957, 2013). "Whole tumour and parenchymal samples demonstrated differential gene expression, with 289 genes significantly overexpressed in the whole tumour, many of which were consistent with stromal gene expression (e.g., COL6A3, COL1A2, POSTN, TIMP2)." (PMID 19401702, 2009). "In agreement with microarray data, COL6A3 expression was drastically reduced in all cell lines tested compared to matched tumors with cell line/tumor ratio of COL6A3 cDNA ranging from 0.03 to 1.5%." (PMID 18086302, 2007). "Overexpression of COL6A3 in GC promotes tumor growth and progression." (PMID 38903804, 2024). "Overexpression of COL6A3 in tumor cells can directly remodel their extracellular matrices (ECMs)." (PMID 39125689, 2024). "Our previous study demonstrated that upregulation of collagen type VI α3 (COL6A3) may promote tumor invasion and metastasis in EOC." (PMID 39125689, 2024). "Overall, these data together showed that COL1A1, COL1A2, and COL6A3 are the key molecules that might regulate the tumor pEMT phonotype by interacting with SDC1 and accelerate the malignant progression of cancer patients." (PMID 38002057, 2023). "Besides, like the CLDN2+ AT2 cells, this COL6A3+ fibroblast subtype was also more significantly enriched by the tumor tissues than the normal ones." (PMID 37488117, 2023). "In particular, genes encoding collagen, including COL1A1, COL1A2, COL6A1, and COL6A3, are upregulated in tumor tissue and also highly expressed in late-stage cancer patients; they are predicted to interact with SDC1 and SDC4 in tumor cells to promote the pEMT phenotype of tumors." (PMID 38002057, 2023).
tumor (continued). "While PDAC-specific splicing of exons 3 and 6 of COL6A3 has been observed in 97% of the paired tumor-adjacent pancreas tissue samples, the presence of COL6A3 transcripts with alternate splicing of exon 4 is almost exclusive to the tumor tissue." (PMID 34901028, 2021). "The percent of stromal cells does not correlate with the junction usage of COL6A3, excluding the possibility that the splicing events is caused by the variability of stroma content in tumor tissues." (PMID 32503434, 2020). "COL6A3 levels are increased in response to cisplatin exposure in tumours." (PMID 23629957, 2013). "Finally, COL6A3 is a member of genes serving to form the tumor vasculature." (PMID 34417465, 2021). "Stromal COL6A3 could promote tumor growth by modulating Hippo and Wnt signaling." (PMID 26338966, 2015). "The supernatant from COL6A3+ TAFs was collected to obtain TAF-conditioned medium (TAF-CM), while the supernatant from tumor cells was collected to generate tumor cell-conditioned medium (TCM)." (PMID 41174767, 2025). "Our findings highlight the critical role of COL6A3+ TAFs in regulating MDM function and spatial distribution, as well as their contribution to fibrotic tumor vasculature formation." (PMID 41174767, 2025). "In short, we identified an exclusive tumor cell subpopulation MP3 in D‐TGCT and confirmed the role of these tumor cells in regulating differentiation of CD34+ Fbs toward APOE+ Fbs and MMP3+ Fbs through COL6A3 − (ITGAV + ITGB8) interaction." (PMID 40126353, 2025). "In this review, we examine the molecular implications of COL6A3 and ETP expression and their effects on tumor growth, metastasis, and therapeutic response." (PMID 41228242, 2025). "Subcluster 1 exhibited pronounced upregulation of extracellular matrix (ECM)‐related genes (COL6A3, COL5A1) in tumor samples compared to normal tissues." (PMID 41057994, 2025). "COL6A3 and COL3A1 are involved in extracellular matrix (ECM) remodeling, which is crucial for tumor progression." (PMID 40427760, 2025). "MMP2, COL6A3, PRRX1, COL1A2, GREM1 and SNAI2 are integral to the EMT process, a key driver of metastasis that allows tumor cells to detach and invade distant tissues." (PMID 39920655, 2025). "In contrast, knockdown of COL6A3 in EOC spheroids inhibited COL6A3 expression in EOC spheroids, which decreased EOC spheroid formation, invasion, tumor growth, and metastasis." (PMID 39125689, 2024). "We confirmed that COL6A3 is secreted from EOC cells and tumor stroma via the exosomal pathway to affect EOC cells and ascites-derived MSC-OCSPCs." (PMID 39125689, 2024). "COL1A2, COL1A1, COL6A3, and SDC1 were expressed at higher levels in tumor tissue compared with normal tissue in the TCGA-BC, TCGA-CRC, and TCGA-ESCA datasets." (PMID 38002057, 2023). "sc-CAFs-NFs analysis revealed a significant increase in CAFs expression of 3 exiting marker genes (FAP, COL11A1 and POSTN) and 2 newly proposed markers (COL6A3 and MFAP2) in all tumor types we studied." (PMID 36263012, 2022). "COL4A1, COL6A3, FAP, and LY6E were up-regulated in the tumor group in the training set, whereas ABCA8, MAMDC2, TMEM100, and TMEM266 were down-regulated." (PMID 36685898, 2022). "Col1a1, Col1a2, Col2a1, Col3a1, and Col5a2, which were commonly found in normal ECM of mouse, pig, and human breast tissues, were also identified in tumor ECM in addition to Col4a2, Col5a1, Col6a1, Col6a2, Col6a3, and Col7a1." (PMID 36547361, 2022). "Our results showed that the methylation levels of COL6A1/2/3 in tumor tissues were significantly lower than in normal tissues, as follows: COL6A1 in ESCA, BRCA, UCEC, and PRAD; COL6A2 in LIHC, HNSC, KIRP, and BLCA; COL6A3 in HNSC, BRCA, UCEC, COAD, and PRAD." (PMID 36167487, 2022). "In particular, we found increased relative expression of MMP1, COL6A1, COL6A3, and TGFB1 in MCTS relative to tumor spheroids." (PMID 34035369, 2021). "The collagen family (COL1A2, COL1A1, COL6A3, and COL5A1), DCN, FBLN1, and POSTN were the most abundant components of the tumor ECM." (PMID 33613617, 2020).
tumor (continued). "Of these probe sets, several genes encoding proteins involved in extracellular matrix (ECM)-tumor interaction and focal adhesion (COL6A3, COL8A1, CTHRC1, THBS2, COMP) were upregulated, whereas ITGA2gene with the same function was downregulated in tumor cells." (PMID 17389037, 2007). "Finally, ECM and fibrosis-related molecules (COL1A1, COL4A1, COL6A3, fibronectin, and LAMC1) were elevated, closely mimicking the desmoplastic tumor microenvironment of HCC." (PMID 41149589, 2025). "Furthermore, we found that MES-like tumor cells and GPNMB+MDMs co-localize in the PAN region, whereas COL6A3+TAFs and ICAM1+MDMs are distributed adjacent to MVP niches for the first time, revealing the unique spatial ecological niches in GBM patients." (PMID 41174767, 2025). "Notably, MES-like tumor cells and GPNMB+ MDMs were predominantly localized to peri-necrotic regions, whereas ICAM1+ MDMs, COL6A3+ TAFs, and endothelial cells were enriched in peri-vascular areas." (PMID 41174767, 2025). "Next, we leveraged the Ivy-GBM cohort to integrate the transcriptional signatures of MES-like tumor cells, ICAM1+ MDMs, GPNMB+ MDMs, COL6A3+ TAFs, endothelial cells, and NK/T cells with distinct histological regions of GBM tissues, estimating the relative proportions of each cell cluster." (PMID 41174767, 2025). "In our integrated analysis, we discovered a unique subpopulation of tumor cells (MP3 cluster) in D‐TGCT that could regulate differentiation of CD34+ Fbs into MMP3+ Fbs and APOE+ Fbs through the COL6A3 − (ITGAV + ITGB8) ligand–receptor pair." (PMID 40126353, 2025). "The predominant predicted tumor-to-microglia interactions in this model were driven by tumor junctional adhesion molecule (JAM) and extracellular matrix (ECM) ligands, such as collagens (e.g., COL4A2, COL6A3) and laminins (e.g., LAMA3, LAMC1)." (PMID 39372744, 2024). "Finally, a cleavage fragment of COL6A3 known as endotrophin recruits macrophages through induction of monocyte chemoattractant protein-1 (MCP1) and increases IL-6 and TNFα in the tumor microenvironment." (PMID 36901727, 2023). "Not only were many collagen genes overexpressed in tumor progression between T1 and T2 stages, but also the mRNA expression of these collagen genes, such as COL1A1, COL1A2, COL3A1, COL5A1, COL5A2, COL6A2, and COL6A3, was highly positively correlated." (PMID 36596829, 2023). "Gene expression of COL1A1, COL1A2, COL6A3, FN1, and THY1 in CAFs as well as COL4A1 and COL4A2 in Angiogenic_EC had a highly significantly positive correlation with the proportion of malignant tumor cells." (PMID 38002057, 2023). "However, these genes had higher methylation levels in tumor tissues, including COL6A1 in KIRC, HNSC, THCA, KIRP, and COAD; COL6A2 in KIRC, LUSC, and BRCA; COL6A3 in LIHC and KIRC." (PMID 36167487, 2022). "CDH11, COL6A3, EDNRA, and SERPINF1 were all negatively correlated with tumor purity." (PMID 36595851, 2022). "Since EMT-related clusters included both EMT-binding proteins (CAVIN1, COL6A1 and COL6A3) and EMT-driving partner proteins (CAVIN1 and COL6A1), a heterogeneous population of cells with EMT potential may reside within the tumor that drive metastasis." (PMID 36249004, 2022). "Substantial differences between tumor and neighboring healthy cortex were found in both interstitial matrix proteins, such as collagen 6 (COL6A1, COL6A2, COL6A3), and basement membrane components such as collagen 4 (COL4A1, COL4A2) and laminins (LAMA5, LAMA4, LAMB1, LAMB2, LAMC1)." (PMID 34884982, 2021). "We showed that genes co-expressed with WISP1 may act as tumor promotors by regulating ECM organization, with the collagen members COL6A3, COL5A1, and COL8A1 being key genes in a majority of cancers." (PMID 32523603, 2020). "Thus, in vivo cells expressing OPN, IL-8 and COL6A3 are co-located with cells expressing AXL in normal and tumor contexts." (PMID 29719832, 2018).
tumor (continued). "Transcripts for the matrix protein Collagen IV-3A (COL6A3) tend to include the cassette exons 3, 4 (not shown) and 6 in tumor samples to a greater extent than in normal samples." (PMID 17192196, 2006). "Additionally, while lower in global rankings, several genes including COL6A3 (extracellular matrix remodeling), FKBP5 (glucocorticoid signaling), IGFBP2 (tumor invasion and angiogenesis), and TPM2 (cytoskeletal stability) appeared prominently in local SHAP plots for specific cancer samples." (PMID 40941703, 2025). "To begin to determine what might be the role of CCN1 expression by CAFs, we used CAF single-cell expression data to identify a group of six genes (PDGFRA, COL1A1, DCN, TAGLN, COL6A3, and LPAR1) that strongly correlated with CCN1 expression, yet were minimally expressed in other tumor cell types." (PMID 38363129, 2024). "Furthermore, the gene expression levels of COL1A1 with SDC1, COL1A2 with SDC1, and COL6A3 with SDC1 were significantly positively correlated in TCGA-BC and TCGA-PDAC, supporting their potential interaction in the surrounding tumor niche." (PMID 38002057, 2023). "Additionally, RNA sequencing of CRC cells with TRIP13 knockdown identified COL6A3, TREM2, SHC3, and KLK7 as downstream targets that may have functional relevance in TRIP13‐mediated tumor growth and metastasis." (PMID 33037736, 2020). "Moreover, COL6A3, DCN, and LUM, which were upregulated after the WNT pulse here, are all typical markers for the switch to a mesenchymal phenotype in lens epithelial and tumor cells." (PMID 33195222, 2020). "Furthermore, SPARC, COL6A3, and FBN1 play an important role in tumor-related immune infiltration and may be ideal targets for immune therapy against PDAC." (PMID 32934754, 2020). "For example, gene expression levels of COL1A1, COL6A3, and FN1 in CAFs as well as COL4A1 and COL4A2 in Angiogenic_EC were correlated with the proportion of the Cancer_Malig subtype in BC and CRC, indicating these pEMT tumor cells might be regulated by COL1A1 in CAFs and COL4A1 in Angiogenic_EC." (PMID 38002057, 2023). "The elevated level of COL6A3 did not have a significant association with overall survival but it was able to predict survival better than the CA19-9 level, a carbohydrate biomarker that is currently the most frequently used biomarker to monitor tumor progression in PDAC patients." (PMID 34901028, 2021). "The cells cultured in MSC medium expressed high levels of COL6A3+ TAF signature genes (COL6A3 and PDGFRA), whereas the tumor cells cultured in DMEM did not express these genes, confirming the accuracy of our isolation method." (PMID 41174767, 2025).